TMEM33 (transmembrane protein 33)
Description:
Acts as a regulator of the tubular endoplasmic reticulum (ER) network by modulating intracellular calcium homeostasis. Mechanistically, stimulates PKD2 calcium-dependent activity (By similarity). Suppresses the RTN3/4-induced formation of the ER tubules. Positively regulates PERK-mediated and IRE1-mediated unfolded protein response signaling. Plays an essential role in VEGF-mediated release of Ca(2+) from ER stores during angiogenesis. Also plays a role in the modulation of innate immune signaling through the cGAS-STING pathway by interacting with RNF26. Participates in lipid metabolism by acting as a downstream effector of the pyruvate kinase/PKM. Forms a complex with RNF5 to facilitate polyubiquitination and subsequent degradation of SCAP on the ER membrane.
Synonyms: FLJ10525; Pom33; 1600019D15Rik; SHINC-3; SHINC3
Tractability: Antibody: UniProt predicts a signal peptide or a membrane-spanning region. PROTAC: ubiquitination databases record sites on it; its protein half-life has been measured.
Gene: Protein-coding gene on chromosome 4 (41,934,403 to 41,960,803, forward strand). Ensembl gene ENSG00000109133.
Subcellular location: Endoplasmic reticulum membrane; Melanosome; Nucleus envelope
Gene Ontology:
Molecular function: protein binding
Biological process: positive regulation of IRE1-mediated unfolded protein response; positive regulation of PERK-mediated unfolded protein response; regulation of endoplasmic reticulum tubular network organization; response to endoplasmic reticulum stress; endoplasmic reticulum tubular network organization; membrane organization
Cellular component: endoplasmic reticulum; endoplasmic reticulum membrane; melanosome; nuclear envelope; membrane
Genetic constraint (gnomAD): Loss-of-function variants: 11 observed, 24.22 expected, observed/expected ratio (o/e) 0.45, 90% interval 0.28 to 0.75. The upper end of that interval is the gene's LOEUF score, 0.75, which puts it in group 3 of 6, group 1 being the genes least tolerant of losing a copy. Missense variants: 226 observed, 271 expected, observed/expected ratio (o/e) 0.83, 90% interval 0.75 to 0.93. Synonymous variants: 95 observed, 101.66 expected, observed/expected ratio (o/e) 0.93, 90% interval 0.79 to 1.11.
Homologues: Orthologues: chimpanzee TMEM33 (100% identical), macaque TMEM33 (100% identical), guinea pig TMEM33 (98% identical), rabbit TMEM33 (98% identical), rat Tmem33 (98% identical), dog TMEM33 (98% identical), mouse Tmem33 (98% identical), tropical clawed frog tmem33 (87% identical), pig TMEM33 (85% identical), zebrafish tmem33 (81% identical), Drosophila melanogaster Kr-h2 (42% identical), Caenorhabditis elegans npp-25 (39% identical).
Diseases named in the same sentence as TMEM33 in open-access papers:
TMEM33 is named in the same sentence as 19 diseases in open-access papers, as found by Europe PMC text mining. Sharing a sentence is not in itself a finding about the gene and the disease. The quoted sentences say what the papers report.
cervical cancer (5 papers, 2022 to 2025). A primary or metastatic malignant neoplasm involving the cervix. "The present study also highlights that ENALA treatment can also be repurposed for cervical cancer treatment, as the increased level of TMEM33 was associated with increased tumor cell proliferation and poor prognosis in cervical cancer." (PMID 40940770, 2025). "Since six tumorigenesis related TMEM33-correlated genes were filtered by bioinformatics tools, we verified their association with TMEM33 in cervical cancer cells." (PMID 35832191, 2022). "TMEM33 expression is increased in cervical cancer and can be used as an independent prognostic marker." (PMID 36338972, 2022). "Subsequently, the prognostic value of TMEM33 in cervical cancer and its role in immune infiltration and cell proliferation were evaluated." (PMID 35832191, 2022). "More importantly, knockdown of TMEM33 in cervical cancer cells decreased the expression of those genes and inhibited cell proliferation." (PMID 35832191, 2022). "High expression of TMEM33 predicted poor prognosis and was considered as an independent prognostic factor and potential therapeutic target for cervical cancer." (PMID 35832191, 2022). "Increased TMEM33 expression correlated with immune cell infiltration and promoted cell proliferation in cervical cancer." (PMID 35832191, 2022). "After we examined the expression of TMEM33 in cervical cancer cells, HeLa and SiHa cells were further selected for the TMEM33 functional study." (PMID 35832191, 2022). "To investigate the expression level of TMEM33 in cervical cancer cells, we performed RT-qPCR and immunoblotting in cervical cancer cell lines HeLa, SiHa, CaSki, H8 and C33A." (PMID 35832191, 2022). "In summary, the molecular networking analysis provided more evidence to deeply understand the potential mechanism of TMEM33 in cervical cancer." (PMID 35832191, 2022). "CCK-8 assay and colony formation assay were performed to investigate the carcinogenesis role of TMEM33 in cervical cancer cell proliferation." (PMID 35832191, 2022). "In cervical cancer, TMEM33 could potentially be leveraged as the marker used to predict prognosis and immune infiltration, with its increased expression associated with higher cell proliferation rates." (PMID 40191724, 2025). "Finally, we examined the expression of TMEM33 in cervical cancer cells and uncovered its role in facilitating cell proliferation." (PMID 35832191, 2022). "A study indicated that transmembrane protein 33 (TMEM33) was implicated in tumor recurrence, while its role in cervical cancer has not been elucidated." (PMID 35832191, 2022). "In addition, we examined the mRNA expression of RNF4, OCIAD1, TMED5, DHX15, MED28, and LETM1 in TMEM33 knockdown cervical cancer cells." (PMID 35832191, 2022). "Moreover, cervical cancer patients with higher TMEM33 levels showed strikingly worse OS, PFI, and DSS." (PMID 35832191, 2022). "The last issue of interest we addressed was the role of TMEM33 in cervical cancer cells." (PMID 35832191, 2022). "Therefore, highly expressed TMEM33 in cervical cancer may potentially impact tumor immunity thereby contributing to oncogenesis." (PMID 35832191, 2022). "Consequently, TMEM33 dysregulation may contribute to the tumorigenesis of cervical cancer." (PMID 35832191, 2022).
breast carcinoma (3 papers, 2019 to 2024). "Thus, renal tubular epithelial cells and breast cancer cells show a different susceptibility to the deleterious effects of TMEM33 expression, with the possible differential involvement of cell cycle components or other elements that contribute to cancer." (PMID 31048699, 2019). "In breast cancer cells, PKM2 controls NFE2L1 cleavage and the transcriptional downstream transmembrane protein 33 (TMEM33), which regulates activation of SREBPs and lipid metabolism." (PMID 39061827, 2024). "In the human breast cancer cell line MCF-7, TMEM33 interacted and stimulated both the PERK/p-eIF2α/ATF4/CHOP and IRE1α-XBP1-S signaling pathways." (PMID 31048699, 2019). "TMEM33 is highly expressed in breast cancer cells and up-regulated in early recurrent breast cancer specimens compared with non-recurrent breast tumors, however, its expression in the majority of cancers has not been well characterized." (PMID 35832191, 2022).
acute kidney injury (2 papers, 2019 to 2022). Sudden and sustained deterioration of the kidney function characterized by decreased glomerular filtration rate, increased serum creatinine or oliguria. "Together, our results identify a key role for TMEM33 in the regulation of intracellular calcium homeostasis of renal proximal convoluted tubule cells and establish a causal link between TMEM33 and acute kidney injury." (PMID 31048699, 2019). "The highest scorings proteins associate with IP3-receptors in the ER, including: TMEM33 (p = 4.33E–06; log2FC = 20.46), a Ca2+ regulator affecting acute kidney injury, ERLINs, which regulate IP3 receptors, DNAJs regulating degradation, and ARFs controlling G-protein coupled receptors (GPCRs)." (PMID 34663908, 2022). "In the same line, it is interesting to note that during ischemic acute renal failure, affecting primarily the proximal tubule, a pronounced upregulation of intracellular PC2 (the partner of TMEM33) was reported." (PMID 31048699, 2019). "Finally, we establish a functional link between TMEM33 and acute kidney injury (AKI), while Pkd2-dependent cystogenesis is independent of TMEM33." (PMID 31048699, 2019).
cervical squamous cell carcinoma (1 paper, 2022). A squamous cell carcinoma arising from the cervical epithelium. "In the present study, we identified TMEM33 was markedly overexpressed in Cervical Squamous Cell Carcinoma and Endocervical Adenocarcinoma (CESC) from The Cancer Genome Atlas (TCGA) and Gene Expression Omnibus (GEO) dataset." (PMID 35832191, 2022).
cyst (1 paper, 2019). A sac-like closed membranous structure that may be empty or contain fluid or amorphous material. "In other words, does TMEM33 invalidation aggravate cyst formation caused by Pkd2 knock-down and can we probe the functional role of ER PC2 in renal cystogenesis taking advantage of its activator TMEM33?" (PMID 31048699, 2019).
lung adenocarcinoma (1 paper, 2025). A carcinoma that arises from the lung and is characterized by the presence of malignant glandular epithelial cells. "This study aims to investigate the potential role of Transmembrane protein 33 (TMEM33) in the development of lung adenocarcinoma." (PMID 40191724, 2025). "We leveraged The Cancer Genome Atlas (TCGA) database to analyze the connection between TMEM33 expression to the prognosis of lung adenocarcinoma (LUAD)." (PMID 40191724, 2025).
lung carcinoma (1 paper, 2025). "Our study carried out a comprehensive evaluation of how TMEM33 affects lung cancer cell proliferation, invasion, and stemness, highlighting the potential implication of the miR-214-3p/TMEM33 pathway in LUAD progression." (PMID 40191724, 2025). "In both cellular and animal models, we further demonstrated that TMEM33 knockdown could effectively suppress the aggressiveness of lung cancer cells, impeding tumor growth and inhibiting metastasis in the mouse model." (PMID 40191724, 2025). "Additionally, TMEM33’s biological role was confirmed in the mouse xenograft model through lung cancer transplantation and metastasis studies." (PMID 40191724, 2025). "Considering that TMEM33 expression is influenced by various signals, including miR-214-3p, and is tied to LUAD prognosis, it may be the target for treating lung cancer." (PMID 40191724, 2025). "Nevertheless, how TMEM33 overexpression impinges on the aggressiveness of lung cancer cells and tumor progression has not yet been explored." (PMID 40191724, 2025).
renal carcinoma (1 paper, 2025). A carcinoma arising from the epithelium of the renal parenchyma or the renal pelvis. "TMEM33 (transmembrane protein 33) is known as an oncogene with elevated levels present in cervical and renal cancers." (PMID 40191724, 2025).
squamous cell carcinoma (1 paper, 2022). A carcinoma arising from squamous epithelial cells. "The expression of TMEM33 was higher in adenosquamous compared with squamous cell carcinoma of CESC." (PMID 35832191, 2022).
virus infections (1 paper, 2021). "Given that TMEM33 reduces the TBK1 kinase activity and fish TBK1 plays a vital role in defending against virus infections, the modulation of TMEM33 regulation of the TBK1-mediated cellular antiviral immune response was evaluated." (PMID 33600488, 2021).
cancer (8 papers, 2019 to 2026). A tumor composed of atypical neoplastic, often pleomorphic cells that invade other tissues. "In addition, the findings of pan-cancer survival assays suggested that TMEM33 expression was linked to the prognosis of patients who were diagnosed with KIRC, SKCM, and CC." (PMID 37273452, 2023). "Investigation into the potential roles of TMEM33 in other cancer hallmarks beyond proliferation, invasion, and stemness is warranted." (PMID 40191724, 2025). "TMEM33 is negatively regulated by miR-214-3p, and its knockdown significantly reduces cancer cell proliferation, invasion, and stem-like properties both in vitro and in vivo." (PMID 40191724, 2025). "The present work comprehensively assessed TMEM33 expression patterns, their clinical implications, and their effects on cancer cell proliferation, invasion, and stemness using samples from patients, cell cultures, and animal models." (PMID 40191724, 2025). "To verify these results, we analyzed 86 LUAD tumors together with 86 matched non-carcinoma samples, confirming overexpression of TMEM33 in the cancerous tissues through RT-qPCR." (PMID 40191724, 2025). "In pan-cancer assays, it was found that TMEM33 was present at a high level in many different kinds of tumors." (PMID 37273452, 2023). "During our investigation of pan-cancer, we discovered that TMEM33 was overexpressed in two of the tumors." (PMID 37273452, 2023). "After that, we conducted pan-cancer assays and found that TMEM33 was present at a high level in many different kinds of tumors, including ACC, LUAD, and PRAD." (PMID 37273452, 2023). "Among 33 cancer types, TMEM33 was significantly highly expressed in 24 cancers compared with normal tissues." (PMID 35832191, 2022). "For TCGA tumors and cancer-adjacent normal tissues, TMEM33 expression was significantly up-regulated in 14 cancer types." (PMID 35832191, 2022). "Based on the TCGA and GTEx databases, we examined the expression profile of TMEM33 in pan-cancer analysis." (PMID 35832191, 2022). "Given limited previous research with regard to TMEM33 in cancer, we performed functional analysis based on GO, KEGG and GESA in CESC." (PMID 35832191, 2022). "TMEM33, or transmembrane protein 33, is a transmembrane protein involved in endoplasmic reticulum stress-responsive events in cancer cells." (PMID 31781476, 2019). "Accumulating evidence also suggested that genes that support cancer development, like TMEM33, could be useful as indicators for diagnosing and treating cancer patients." (PMID 40191724, 2025). "Exploring the role of targeting the miR-214-3p/TMEM33 pathway in cancer treatment could open new treatment avenues." (PMID 40191724, 2025). "Previous findings suggest that TMEM33 has an important effect on cancer development." (PMID 40191724, 2025). "It was previously reported that transmembrane protein 33(TMEM33) could report a poor prognosis in several cancers." (PMID 37273452, 2023). "Through bioinformatics analysis on TCGA and GTEx datasets, we found TMEM33 was up-regulated in 24 of 33 cancer types compared with normal tissues, indicating TMEM33 might be involved in tumorigenesis." (PMID 35832191, 2022). "Although the role of TMEM33 is gradually revealed in different aspects, its expression in cancer and implications in tumorigenesis are largely unknown, warranting further exploration." (PMID 35832191, 2022). "This suggests that TMEM33 may be a potential therapeutic target for cancer immunotherapy." (PMID 37273452, 2023). "Moreover, the TMEM33 expression level was remarkably positively correlated with similar genes of RNF4, OCIAD1, TMED5, DHX15, MED28 and LETM1, which have been reported to be implicated in tumorigenesis of various cancers." (PMID 35832191, 2022). "The overexpression of TMEM33 was also confirmed in 20 randomly selected pairs of LUAD and matched non-carcinoma tissues by IHC." (PMID 40191724, 2025).
cancer (continued). "RRA analysis further identify a set of MSI1-bound genes in G3 MB, including TMEM33, SFNX and HIPK1, as cancer-selective downstream targets for therapeutic drug targeting (i.e., not bound in NSC)." (PMID 36473869, 2022). "In our study, we found TMEM33 was up-regulated in CESC and most other cancer types." (PMID 35832191, 2022). "Moreover, TMEM33 was shown to be a stress-inducible ER protein that modulates the unfolded protein response signaling by interacting with PERK and IRE1α in cancer cells." (PMID 31048699, 2019). "The other five genes (TMEM33, UBE2H, ATAB2D, ZBT44 and STRN) were not reported in cancers." (PMID 37407973, 2023).
tumor (5 papers, 2022 to 2026). "TMEM33 knockdown cells exhibit reduced tumor aggressiveness in vivo, as evidenced by the decreased tumor weight and volume in the subcutaneous injection model, and they decreased the number of metastatic nodules in the lungs in the tail vein injection model." (PMID 41596760, 2026). "As a result, xenograft tumor weight and volume significantly decreased in the sh-TMEM33 group relative to the control group." (PMID 40191724, 2025). "The current study is aimed at investigating the potential prognostic value of TMEM33 and its relevance to the tumor microenvironment in CC in a comprehensive manner." (PMID 37273452, 2023). "In summary, our study demonstrated that TMEM33 functions as an oncogene in LUAD, promoting tumor progression through the Wnt/β-catenin signaling pathway." (PMID 40191724, 2025). "Furthermore, Ki-67, TMEM33, and SOX2 protein expression in tumors from the sh-TMEM33 group exhibited a marked decrease, indicating a decrease in tumor aggressiveness and stemness." (PMID 40191724, 2025). "Additionally, a chi-square test exploring the relation of TMEM33 with various clinicopathological features showed a significant correlation with lymph node metastasis, TNM stage, and tumor differentiation, rather than with age, sex, and tumor size." (PMID 40191724, 2025).
infection (1 paper, 2021). The state of being infected such as from the introduction of a foreign agent such as serum, vaccine, antigenic substance or organism. "At 48 h post-infection, substantially more CPE was observed in the TMEM33 group compared with that in the control cells." (PMID 33600488, 2021).
TMEM33 also shares sentences with these, for which no sentence is quoted: breast tumors (1 paper); endocervical adenocarcinoma (1); hearing loss (1); Hypertension (1); pancreatic cancer (1); renal cystic diseases (1).